SPINK1 (serine peptidase inhibitor Kazal type 1)
Diseases named in the same sentence as SPINK1 in open-access papers (continued):
Sharing a sentence is not in itself a finding about the gene and the disease.
hepatocellular carcinoma (19 papers, 2013 to 2025). A malignant tumor that arises from hepatocytes. "High levels of SPINK1 presented as prognostic and diagnostic biomarkers in hepatocellular carcinoma, promoting cell proliferation and metastasis." (PMID 35219893, 2022). "In BRL-3A hepatocellular carcinoma cells, upregulation of endogenous or exogenous recombinant SPINK1 was noted to be associated with the effect of anti-apoptosis." (PMID 36053457, 2022). "Tumor tissue staining for SPINK1 has been associated with poorer survival in non-serous ovarian cancers and in estrogen receptor- positive breast cancer, and there is potential for SPINK1 to serve as a diagnostic marker for hepatocellular carcinoma." (PMID 30778387, 2019). "Moreover, the elevated expression of SPINK1 was shown to enhance the growth, migration, and invasion of hepatocellular carcinoma cells (HCC) and was associated with poor prognosis in HCC patients." (PMID 38892042, 2024). "SPINK1 mitigates tumor cell apoptosis caused by excessive protease activation through trypsin-like serine protease activity inhibition, with elevated expression significantly correlating with increased vascular invasion and recurrence risk in hepatocellular carcinoma patients." (PMID 41450464, 2025). "A previous study demonstrated that silencing of SPINK1 suppressed the proliferation of hepatocellular carcinoma cells leading to the possibility that SPINK1 possessed oncogenic properties." (PMID 40642078, 2025). "In hepatocellular carcinoma, cisplatin and 5-fluorouracil treatment enhance SPINK1 transcriptional activity and drive chemoresistance via the EGFR-ERK-CDK4/6-E2F2 axis." (PMID 40904507, 2025). "SPINK1 also augmented hepatocellular carcinoma cell proliferation ability in a CCK-8 cell proliferation assay." (PMID 33916984, 2021). "The SPINK1 expression level in another hepatocellular carcinoma cohort was investigated using a tissue assay of 273 paired tumor and paratumor tissues." (PMID 33916984, 2021). "Interleukin 6 (IL6) is an important cytokine produced during chronic hepatitis and is known to increase SPINK1 expression in hepatoma cell lines through an IL6 responsive element in the SPINK1 gene." (PMID 23527199, 2013). "Similarly, in hepatocellular carcinoma single-cell sequencing studies, SPINK1 enhances tumor chemoresistance." (PMID 40904507, 2025). "In hepatocellular carcinoma, SPINK1 promotes tumor proliferation and serves as a prognostic marker." (PMID 40904507, 2025). "SPINK1 overexpression was noted to increase cell migration and invasion associated with epithelial-mesenchymal transition via MAPK and the extracellular-regulated kinase pathway in hepatocellular carcinoma." (PMID 36053457, 2022). "Spink1 promotes cell proliferation and was found upregulated in hepatocellular carcinoma." (PMID 33932122, 2021). "SPINK1 may also play a pivotal role in early hepatocellular carcinoma development because the investigation showed significant demethylation of SPINK1 in early hepatocellular carcinoma compared with HGDNs." (PMID 33916984, 2021). "Furthermore, SPINK1 was overexpressed in up to 70% of human hepatocellular carcinomas, and its expression level exhibited a positive correlation with CDH17." (PMID 33916984, 2021). "In liver cancer, a low SPINK1 expression score was found in cirrhosis patients compared with that in well-differentiated hepatocellular carcinoma (WD-HCC) patients." (PMID 33916984, 2021). "HBV and hepatitis C virus (HCV) upregulate expression of serine protease inhibitor Kazal (SPIK), and SPINK1 is overexpressed in HCV-positive hepatocellular carcinoma (HCC) and thus is a promising prognostic marker for this cancer." (PMID 31240230, 2019). "In addition, a significant difference in SPINK1 expression between WD-HCC and high-grade dysplastic nodules (HGDNs) was observed, suggesting a diagnostic role for SPINK1 in hepatocellular carcinoma." (PMID 33916984, 2021).
hepatocellular carcinoma (continued). "Experimentally, SPINK1 was upregulated in OSCC cell lines (SCC9, SCC25, CAL27, HN4, HN30) compared to HOK, consistent with its oncogenic role in other cancers, such as non-small cell lung cancer (MEK/ERK activation)and hepatocellular carcinoma (Wnt/β-catenin signaling)." (PMID 40904507, 2025). "We aimed to characterize serine protease inhibitor Kazal type 1 (SPINK1) as a gene signature for the early diagnosis, molecular targeting, and prediction of immune checkpoint blockade (ICB) treatment response of hepatocellular carcinoma (HCC)." (PMID 35924241, 2022).
colorectal cancer (18 papers, 1990 to 2025). A primary or metastatic malignant neoplasm that affects the colon or rectum. "Our results reveal that silencing SPINK1 in the SPINK1+ colorectal cancer line (WiDr), which also harbors BRAF mutation, attenuates cell invasion, proliferation, foci formation and anchorage-independent growth in soft agar assay." (PMID 26258891, 2015). "Altered SPINK1 expression has been associated with decreased survival in ovarian and colorectal cancer." (PMID 24865347, 2014). "However, increased SPINK1 secretion was reported to be related to vemurafenib resistance in BRAF V600E-mutant colorectal cancers, indicating the need to target different gene variant subtypes of HCC during chemotherapy (29193645)." (PMID 36246599, 2022). "However, in another study, high SPINK1 expression was associated with a good prognosis in patients with advanced colorectal cancer receiving targeted cetuximab-based therapy." (PMID 35479956, 2022). "Studies in colorectal cancer models demonstrate that SPINK1 enhances STAT3 phosphorylation in an IL-6-dependent manner, thereby promoting tumor cell invasion and metastasis." (PMID 40904507, 2025). "With the exception of gastric malignancy, poor prognosis is found in patients with high SPINK1 expression, including those of pancreas, prostate, ovary, breast, liver, lung and colorectal cancers." (PMID 36053457, 2022). "To understand the relationships among SPINK1, autophagy, and tumor growth, we chose human colorectal cancer (CRC) HT29 cells as the typical objects to be studied." (PMID 37305325, 2022). "We aimed to explore the molecular mechanism that were involved in SPINK1-induced proliferation and clonogenic survival of human colorectal carcinoma (CRC) HT29 cells." (PMID 37305325, 2022). "Collectively, these data indicated that SPINK1 induced-autophagy enhancement in HT29 cells of colorectal carcinoma was likely accomplished via Beclin1 signaling." (PMID 37305325, 2022). "Actually, in colorectal cancer, a high percentage of positive immunohistochemical staining of SPINK1 was observed in cancer patients, suggesting a potential cause of tumorigenesis by abnormal SPINK1 overexpression." (PMID 33916984, 2021). "In a colorectal cancer study, Spink3 (the mouse homolog of SPINK1) heterozygous mice showed a decrease in tumor volume compared with wild-type mice, in addition to induced cell proliferation observed in colon cancer cell lines." (PMID 33916984, 2021). "A connection was observed in the colorectal cancer cell lines Colo205 and HT-29, in which the SPINK1 level was increased by both fibroblast-derived and recombinant IL-6 treatment." (PMID 33916984, 2021). "Clinically, another study using immunohistochemical staining detected the SPINK1 level in a high percentage of colorectal cancer patients." (PMID 33916984, 2021). "SPINK1 and SPINK3 have been suggested to promote the proliferation of colorectal cancer cells and rat liver cells, respectively, through the PI3K/AKT signaling pathway." (PMID 34202399, 2021). "In colorectal cancer, a relatively high SPINK1 expression level correlated with a poor prognosis and a high Ki-67 labeling index." (PMID 33916984, 2021). "We have demonstrated that SPINK1 knockdown in the colorectal cancer cell line WiDr abrogated cell proliferation, invasion and anchorage-independent growth in soft agar assay." (PMID 26258891, 2015). "We studied the prognostic value of immunohistochemical expression of EGFR and concomitant expression of EGFR and TATI/SPINK1 in a series of 619 colorectal cancer patients." (PMID 24204699, 2013). "We have recently shown that tissue expression of TATI/SPINK1 is an indicator of favourable prognosis in colorectal cancer patients." (PMID 24204699, 2013). "In conclusion, to the best of our knowledge, we show for the first time that concomitant immunoexpression of EGFR and TATI/SPINK1 is an independent prognostic marker for favourable prognosis in colorectal cancer patients." (PMID 24204699, 2013).
colorectal cancer (continued). "Further studies are necessary to better understand the association between TATI/SPINK1 and EGFR in colorectal cancer and for evaluating the potential use of this marker combination to predict treatment response." (PMID 24204699, 2013). "Three samples of normal liver from patients who had undergone liver resection for colorectal cancer metastases also showed SPINK1 expression in the large bile duct epithelium." (PMID 23527199, 2013). "SPINK1 also functions as a prognostic marker in colorectal cancer, gastric cancer, and renal cell carcinoma, with differential expression observed across multiple solid tumors, including but not limited to ovarian cancer, bladder cancer, gallbladder cancer, lung cancer, and breast cancer." (PMID 40904507, 2025). "Additionally, an immunoreactivity study of colorectal cancer showed a positive Pearson’s correlation between SPINK1 and EGFR intensity." (PMID 33916984, 2021). "In addition, both SPINK1 and IL-6-induced SPINK1 expression augmented cell motility by regulating STAT3 signaling in colorectal cancer." (PMID 33916984, 2021). "Furthermore, another colorectal cancer study characterized the role of SPINK1 in promoting cancer metastasis using chicken chorioallantoic membrane assays, murine xenograft studies, and metastasis models." (PMID 33916984, 2021). "As supporting evidence, the distinct pathological properties of SPINK1 were reproduced by extended studies that recruited individual cohorts of human breast cancer (BCa) and colorectal cancer (CRC) patients (P < 0.01 for BCa and P < 0.05 for CRC cohorts by log-rank test, respectively)." (PMID 30333494, 2018). "Notably, in colorectal cancer, SPINK1 has been shown to activate the EGFR/MAPK signaling pathway, thereby promoting cancer progression, which may be related to the tissue-specific origin characteristics of the tumor." (PMID 40904507, 2025). "The interaction between SPINK1 and the JAK-STAT3 pathway has also been observed in both ovarian cancer and colorectal cancer." (PMID 40904507, 2025). "SPINK1 promotes a tumorigenic phenotype of colorectal cancer (CRC) by activating the PI3K/AKT and MAPK/ERK signaling pathways, and SPINK1-positive WiDr cells are sensitive to AKT and MEK inhibitors." (PMID 35223512, 2022). "Here we show that concomitant immunoexpression of EGFR and TATI is an independent prognostic factor for favorable survival in colorectal cancer, and it is a stronger prognostic factor than EGFR or TATI/SPINK1 alone." (PMID 24204699, 2013). "Here we show that in roughly two out of three colorectal carcinoma samples EGFR and TATI/SPINK1 are co-expressed." (PMID 24204699, 2013). "In this study, we showed a new Beclin1-associated autophagic pathway which had involved in SPINK1-induced proliferation of HT29 cells, and this autophagy-related, possible signaling of the action in colorectal cancer development have not yet been unraveled." (PMID 37305325, 2022). "As a matter of fact, a high percentage of positive immunohistochemical staining of SPINK1 was observed in colorectal cancer patients, and interestingly, Chang Hyeok Ahnalso noticed that the increased expression of Beclin-1 was detected in 95% of the tumor tissues of the CRC patients." (PMID 37305325, 2022).
ovarian carcinoma (13 papers, 1995 to 2025). A malignant neoplasm originating from the surface ovarian epithelium. "SPINK1 was originally named tumor associated tissue inhibitor (TATI) when it was first isolated from the urine of ovarian cancer patients." (PMID 30778387, 2019). "In ovarian cancer, expression of SPINK1 in tumor tissue was previously found to be associated with poorer survival in a group of 56 stage 3 and 4 ovarian cancer patients." (PMID 26437224, 2015). "We have also evaluated the expression of tumor SPINK1 protein in a large cohort of patients with ovarian cancer and have assessed associations with tumor morphology, stage, grade, and overall survival." (PMID 26437224, 2015). "Notably, SPINK1 shows promise as an early diagnostic biomarker: its concentration increases by 1000-fold in malignant ovarian tumors, and it exhibits diagnostic relevance in both hepatocellular and pancreatic malignancies." (PMID 40904507, 2025). "As these EGFR signaling pathways have been extensively linked to proliferation in ovarian cancer, activation of these pathways by SPINK1 offers a plausible mechanism by which SPINK1 may exert its proliferative effects in cell culture." (PMID 26437224, 2015). "Another study group extracted SPINK1 from the urine of ovarian cancer patients and further characterized its properties." (PMID 38093163, 2023). "SPINK1, which is also known as tumor-associated trypsin inhibitor (TATI), was further isolated from the urine of ovarian cancer patients by another research group." (PMID 33916984, 2021). "In ovarian cancer, cancer cell proliferation was induced by SPINK1 and was further abolished by EGFR inhibitor." (PMID 33916984, 2021). "SPINK1, also known as tumor-associated trypsin inhibitor (TATI) or pancreatic secretory trypsin inhibitor (PSTI) was previously discovered in the urine of ovarian cancer patients." (PMID 31959826, 2020). "In our own work we find phosphorylation of the intracellular domain of EGFR as well as phosphorylation of AKT and ERK upon treatment of ovarian cancer cells with SPINK1, consistent with activation of EGFR downstream pathways." (PMID 30778387, 2019). "We have shown that SPINK1 plays an essential role in ovarian cancer cell survival under attachment free conditions." (PMID 30778387, 2019). "Non-adherent cell survival was increased in a dose-dependent manner when treating ovarian cancer cell lines with recombinant SPINK1 protein." (PMID 30778387, 2019). "For both the UWB1.289 and OVCA420 cell lines, we observed significantly reduced EdU incorporation in cells in which SPINK1 expression was suppressed establishing a functional role for endogenous SPINK1 in promoting proliferation of ovarian cancer cells." (PMID 26437224, 2015). "In this study, using cell culture models of invasive epithelial ovarian cancer, we find that SPINK1 directly promotes ovarian cancer cell proliferation and resistance to anoikis." (PMID 26437224, 2015). "In this study, we identify the serine protease inhibitor Kazal type 1 (SPINK1) as a potential therapeutic target for a subset of ovarian cancers." (PMID 26437224, 2015). "Our results implicate SPINK1 as a driver of proliferation and as a potential therapeutic target in a subset of ovarian cancers spanning multiple histological types." (PMID 26437224, 2015). "To measure the specific effect of SPINK1 on ovarian cancer cell proliferation, we next carried out EdU incorporation assays." (PMID 26437224, 2015). "The key advances of the present study are the identification of SPINK1 as a driver of proliferation in ovarian cancer cell lines as well as a factor responsible for protecting ovarian cancer cells from anoikis." (PMID 26437224, 2015). "In our functional studies, we found that even very low-expressing ovarian cancer cells can show strong dependence of proliferation on SPINK1." (PMID 26437224, 2015).
ovarian carcinoma (continued). "We also evaluate tissue expression of SPINK1 in a patient cohort of nearly 500 women with invasive epithelial ovarian cancer, comprehensively assessing prognostic significance in relation to stage, grade, and histological subtypes." (PMID 26437224, 2015). "Moreover, SPINK1 is involved in tumor metastasis, acts as a prognostic biomarker for lung cancer, and acts as a predictive biomarker for ovarian cancer." (PMID 34202399, 2021). "Our results suggest that SPINK1 could have clinical utility as a prognostic tissue biomarker in patients with these relatively rare subtypes of ovarian cancer." (PMID 26437224, 2015). "To assess whether, in addition to its effect on proliferation, SPINK1 may promote cell survival under anchorage independent conditions, we measured ovarian cancer cell survival on ultra-low attachment plates in the absence and presence of rSPINK1." (PMID 26437224, 2015). "In the present study, while our cohort was comprised of patients with a typical distribution of ovarian tumor subtypes, we found SPINK1 to be associated with poor survival specifically in the subset of patients with nonserous ovarian cancers." (PMID 26437224, 2015). "To probe the mechanism through which SPINK1 may protect ovarian cancer cells from anoikis, we assessed the ability of alternative trypsin inhibitors BPTI and SBTI to recapitulate the effect of rSPINK1." (PMID 26437224, 2015). "Having implicated SPINK1 as an autocrine factor capable of promoting ovarian cancer cell proliferation and survival, we next aimed to define the patient group in which SPINK1 may play a prominent role in driving ovarian tumor growth." (PMID 26437224, 2015). "Our discovery that SPINK1 protects ovarian cancer cells from anoikis, and that other similar trypsin inhibitors can recapitulate this effect, likewise poses additional questions, chiefly among them the identity of the protease target(s) of SPINK1 responsible for this effect." (PMID 26437224, 2015). "We conclude from these analyses that SPINK1 is prognostic for poor survival specifically in nonserous subtypes of epithelial ovarian cancer, and within this broad category, the association of SPINK1 with poor survival spans multiple morphological subtypes." (PMID 26437224, 2015). "Intriguingly, our data point to dual mechanisms by which SPINK1 can promote ovarian cancer growth and progression: it appears to stimulate proliferation through an EGFR-dependent mechanism, while promoting resistance to anoikis through a serine protease-dependent, EGFR-independent mechanism." (PMID 26437224, 2015). "Given that ovarian cancer progresses through dissemination, establishment and growth of prolific metastases on the peritoneum and omentum, these novel functions of SPINK1 assist in multiple stages of progression, via multiple mechanisms that here we have begun to elucidate." (PMID 26437224, 2015). "Alternatively, it may be that a more complete blockade of the oncogenic activities of SPINK1 in ovarian cancer can be achieved through direct targeting of SPINK1 itself." (PMID 26437224, 2015). "To assess the potential functional importance of SPINK1 for ovarian cancer cell growth, we initially identified four commonly used epithelial ovarian cancer cell lines spanning a broad range of endogenous expression levels of SPINK1 as assessed by qRT/PCR of transcripts." (PMID 26437224, 2015). "Given that SPINK1 promoted ovarian cancer cell growth and survival in our cell culture models, SPINK1 staining might have been expected to correlate with later stage and higher grade, rather than the associations with earlier stage and lower grade that we observed." (PMID 26437224, 2015). "In the present study, we have identified SPINK1 as a tumor-produced autocrine factor that can contribute to both the proliferative potential and the anoikis resistance of epithelial ovarian cancer cells, and thus plays a functional role in driving ovarian cancer growth and progression." (PMID 26437224, 2015).